GPR55 (G protein-coupled receptor 55)
Diseases named in the same sentence as GPR55 in open-access papers (continued):
Sharing a sentence is not in itself a finding about the gene and the disease.
carcinosarcoma (1 paper, 2021). A malignant tumor composed of a mixture of carcinomatous and sarcomatous elements. "GPR55 staining in serous EC samples, was stronger in the glandular epithelial than in the stromal cells, whilst in carcinosarcoma, immunoreactive staining was more uniform and very intense in all cell types." (PMID 34324032, 2021). "Further analyses of these data indicated that although the H-scores varied between tumour types, GPR55 staining was significantly higher in all grades of Type 1 EC and in both carcinosarcoma and serous EC than in control tissue (lower series of panels)." (PMID 34324032, 2021).
cardiac arrhythmia (1 paper, 2023). Any disturbances of the normal rhythmic beating of the heart or MYOCARDIAL CONTRACTION. "Even non-cannabinoids receptors, such as GPR55, peroxisome proliferator-activated receptor (PPAR), TRP channels, and β-adrenoceptors could modulate ion cardiac channel and alter cardiac regulations, thus leading to cardiac arrhythmias." (PMID 36675144, 2023).
cardiomyopathy (1 paper, 2014). A disease of the heart muscle or myocardium proper. "Therefore it is possible that the profibrogenic effect of CB1, previously documented in an experimental model of doxorubicin-induced cardiomyopathy, may be unimpeded in the mature mice lacking GPR55 thus resulting in the development of mild cardiac fibrosis." (PMID 25275556, 2014).
catalepsy (1 paper, 2021). A nervous system disorder characterized by diminished responsiveness and consciousness, and rigidity of the body. "Similar benefits have been observed with other GPR55-acting compounds using additional experimental models, such as MPTP-lesioned mice and a murine model of haloperidol-induced catalepsy, and the same happens with more recent studies conducted by Martínez-Pinilla and coworkers." (PMID 34946726, 2021).
Cerebral ischemia (1 paper, 2024). Restriction of arterial blood supply to the brain associated with insufficient oxygenation to support the metabolic requirements of the tissue. "In this report, our results indicate that the GPR55 antagonist, ML-193, applied 6 h after stroke induction safeguarded against cerebral ischemia reperfusion injury." (PMID 38334672, 2024).
cervix cancer (1 paper, 2023). "Our results showing BMMC migration towards cervix cancer cells led to the hypothesis that the LPI/GPR55 axis could play a role in the incorporation of MCs in that type of cancer." (PMID 37047288, 2023).
colorectal adenocarcinoma (1 paper, 2021). The most common type of colorectal carcinoma. "A similar trend was observed in SW480 colorectal adenocarcinoma cells upon knockdown of MAPK1 (ERK2) or RAF1 (c-RAF/Raf-1) genes, highlighting the involvement of mitogen-activated protein kinases (MAPKs) in the regulation of GPR55." (PMID 34948125, 2021).
COVID-19 (1 paper, 2022). A disease caused by infection with severe acute respiratory syndrome coronavirus 2. "LPI also acts on GPR55, suggesting that the elevation of LPI during the later phase of severe COVID-19 might accelerate the pathogenesis of COVID-19-associated kidney injuries." (PMID 36357929, 2022). "In contrast, the upregulation of LPG in patients with severe COVID-19 might contribute to the acceleration of inflammation, since LPG exerts agonist activities with proinflammatory GPR55." (PMID 36357929, 2022).
cutaneous T-cell lymphoma (1 paper, 2021). "GPR55 was detected in two types of cancers: papillary serous carcinoma and cutaneous T-cell lymphoma." (PMID 34948125, 2021).
demyelinating disease (1 paper, 2026). A broad group of disorders that affect the myelin sheaths that cover the neurons. "Altogether, our findings identify CB1R/GPR55 heteromers as novel modulators of OLG resilience and highlight their potential as therapeutic targets for promoting neuroprotection and remyelination in demyelinating diseases such as MS." (PMID 41776092, 2026).
hearing loss (1 paper, 2026). "Nevertheless, whether GPR55 plays a role in CDDP-induced hearing loss remains unclear." (PMID 41981055, 2026).
hyperlipidemia (1 paper, 2021). "First, LPI receptor GPR55 is expressed in human and mouse aortic endothelial cells as well as other aortic cell types and is upregulated in hyperlipidemic conditions, suggesting that LPIs/GPR55 signaling is increased in aortic endothelial cells in cardiovascular diseases such as hyperlipidemia." (PMID 34912867, 2021).
infarction (1 paper, 2024). A localised pathological necrosis of tissue resulting from obstruction of the blood supply usually by a thrombus, an embolus, or vascular torsion. "Treatment with a specific GPR55 antagonist, ML-193, resulted in a 34% ± 5% improvement in the infarction area, measured via the TTC stain." (PMID 38334672, 2024). "GPR55 inactivation, with a potent GPR55-specific antagonist, ML-193, starting 6 h after tMCAO or the absence of the GPR55 in mice (GPR55 knock out (GPR55ko)) resulted in a reduced infarction volume, improved neurological outcomes, and decreased splenic responses." (PMID 38334672, 2024).
influenza (1 paper, 2021). An acute viral infection of the respiratory tract, occurring in isolated cases, in epidemics, or in pandemics; it is caused by serologically different strains of viruses (influenzaviruses) designated A, B, and C, has a 3-day incubation period, and usually lasts for 3 to 10 days. "Drugs triggering GPR55 upregulation in the immune cells were identified, namely tofacitinib (immunosuppressant acting as janus kinase inhibitor), canakinumab (anti-inflammatory monoclonal antibody targeting interleukin-1β), and an influenza vaccine." (PMID 34948125, 2021).
insomnia (1 paper, 2022). A sleep disorder characterized by difficulty in falling asleep and/or remaining asleep. "It would also be interesting to explore the effects of these phytocannabinoids in other disease models in which T-type channels and GPR55 play a role, such as in models of insomnia, pain, and gastrointestinal disorders." (PMID 36386164, 2022).
ischemia (1 paper, 2024). A hypoperfusion of the BLOOD through an organ or tissue caused by a PATHOLOGIC CONSTRICTION or obstruction of its BLOOD VESSELS, or an absence of BLOOD CIRCULATION. "Considering these outcomes collectively, we propose that inhibiting GPR55 yields substantial neuroprotective effects post-ischemia." (PMID 38334672, 2024).
leukemia (1 paper, 2021). A malignant (clonal) hematologic disorder, involving hematopoietic stem cells and characterized by the presence of primitive or atypical myeloid or lymphoid cells in the bone marrow and the blood. "CD8+ T-cells engineered with a chimeric CD19 antigen receptor (CAR-T cells) displayed GPR55 upregulation when stimulated with leukemia cells expressing CD19." (PMID 34948125, 2021).
leukoaraiosis (1 paper, 2009). "An interaction between NMUR1 (a G-protein coupled activator that appears to be involved in regulation of food intake) and GPR55 (a G-protein coupled receptor) also points to genetic variation in signal transduction pathways playing a role in leukoaraiosis development." (PMID 19351393, 2009).
lymphoblastic leukemia (1 paper, 2021). "In in vitro studies involving CAR-T cells, it was shown that co-culture with a lymphoblastic leukemia cell line activated CAR-T cells, which responded with increased expression of GPR55." (PMID 34948125, 2021).
mesothelioma (1 paper, 2022). A usually malignant and aggressive neoplasm of the mesothelium which is often associated with exposure to asbestos. "We found that both CBD and CBG produced a dramatic increase in the expression of genes encoding the cannabinoid CB1 receptor, GPR55, and the 5-HT1A receptor in all three mesothelioma cell lines." (PMID 35954477, 2022). "In all three mesothelioma cell lines, both CBD and CBG robustly upregulated mRNA for the cannabinoid CB1 receptor (CNR1), G protein-coupled receptor 55 (GPR55) and the 5-HT1a receptor (HTR1A)." (PMID 35954477, 2022).
migraine (1 paper, 2025). "GPR55 is expressed in high amounts in the brain, but its potential involvement in migraine pathology is complex and far from being understood." (PMID 40630421, 2025). "Clearly, the effect of phytocannabinoids and endocannabinoids on migraine through GPR55 activation is dependent on the cannabinoid employed and if GPR55 is present in a heteromer with CB receptors." (PMID 40630421, 2025). "The involvement of GPR55 in migraine pathology is still unclear due primarily to its agonist dependence and the dearth of preclinical studies." (PMID 40630421, 2025). "Currently, there are no clinical or preclinical studies that directly implicate GPR55 in migraine pathology." (PMID 40630421, 2025).
neuropathy (1 paper, 2023). A disorder affecting the nervous system that manifests with pain, tingling, numbness, and/or muscle weakness. "We analyzed genes known to be targeted by cannabigerol and other cannabinoids, including Cnr1, Cnr2, Gpr55, Faah, Mgll, Adra2a-c, Pparg, or to have been previously published as volatile in a cisplatin-induced neuropathy setting in DRG, including Drd2, Gfap, and Oprm1." (PMID 37895913, 2023).
non-alcoholic fatty liver diseases (1 paper, 2021). "Therefore, the present data suggest the pro-steatotic function of GPR55 signaling in hepatocytes and provide a potential therapeutic target for non-alcoholic fatty liver disease." (PMID 33803038, 2021).
nyctalopia (1 paper, 2021). "Modulation of GPR55 by either blocking GPR55 (impaired retinal function, e.g., nyctalopia) or by activating it (increased retinal function, e.g., hyper-scotopia) impacts solely scotopic retinal function." (PMID 34831383, 2021).
ovarian tumour (1 paper, 2015). "Although beyond the scope of this study, it would be of interest to study the effect of the pharmacological GPR55 inhibitor CID16020046 on ovarian tumour size and vascularity in mice, and furthermore to investigate the involvement of ovarian tumour angiogenesis in GPR55 knockout mice in vivo." (PMID 25989290, 2015).
pancreatitis (1 paper, 2020). Inflammation of the pancreas. "Comparable to our data, the GPR55 agonist O-1602 significantly reduced the levels of IL-6 both in plasma and pancreas tissue in mice with cerulein-induced pancreatitis." (PMID 32210914, 2020).
Sensory neuropathy (1 paper, 2017). Peripheral neuropathy affecting the sensory nerves. "Thus, agonists of cannabinoid receptors and GPR55 could be useful therapeutic agents for the management of NRTI-induced painful sensory neuropathy." (PMID 28373843, 2017).
Sepsis (1 paper, 2016). Sepsis is defined as life-threatening organ dysfunction caused by a dysregulated host response to infection. "There is a growing body of evidence for a pro-inflammatory role of GPR55 in sepsis, suggesting that selective GPR55 antagonists have a potential as a modulators of the immune response, and can be designed as a therapeutic target in sepsis." (PMID 27597829, 2016). "In our laboratory, we demonstrated that GPR55 antagonists, CID16020046, and O-1918, reduced LPS-induced leukocyte-endothelial interactions in experimental models of sepsis in mice." (PMID 27597829, 2016).
skin inflammation (1 paper, 2020). "In addition, CB2 agonists suppress skin inflammation by inhibiting inflammatory cell migration, and GPR55, which is found in mast cells, has anti-inflammatory effects by inhibiting mast cell-mediated release of nerve growth factor and reducing angiogenesis." (PMID 32063982, 2020).
Stroke (1 paper, 2024). Sudden impairment of blood flow to a part of the brain due to occlusion or rupture of an artery to the brain. "Our data demonstrate that the GPR55 antagonist ML-193 significantly increased Treg numbers in the brain 3 days post-stroke." (PMID 38334672, 2024). "Spleen size was measured at 3 days post-stroke in mice, and indeed, tMCAO led to a 32.6% reduction in spleen size, whereas treatment with ML-193, a specific GPR55 antagonist, diminished these effects by almost 93%." (PMID 38334672, 2024). "The orphan G protein-coupled receptor 55 (GPR55)’s connection to inflammatory processes has been recently reported; however, its role in stroke remains to be discovered." (PMID 38334672, 2024). "While the involvement of CB receptors in stroke and inflammation is well documented, information concerning GPR55’s role in stroke physiology remains scarce." (PMID 38334672, 2024). "GPR55 activation and contribution to inflammation have been reported; however, its function in stroke remains to be discovered." (PMID 38334672, 2024). "GPR55 inactivation noticeably attenuated the after-stroke decrease in spleen size and decreased CD4+T-cell spleen egress in tMCAO mice." (PMID 38334672, 2024). "In this study, utilizing experimental stroke models, we have shown that augmenting Treg numbers following a stroke—via GPR55 inactivation—facilitates white matter restoration and enhances functional recovery." (PMID 38334672, 2024). "With this goal in mind, mice were subjected to tMCAO (1 h occlusion followed by reperfusion), and 6 h after stroke onset, they were injected with IP and 1 μg/mL ML-193, the most potent GPR55 antagonist, or with the vehicle only (0.001% DMSO) as a control, respectively." (PMID 38334672, 2024). "Consequently, employing GPR55 antagonists could serve as a pivotal new avenue for stroke therapies, either independently or in combination with other treatment modalities." (PMID 38334672, 2024). "We decided to check if GPR55 inhibition could affect Treg numbers in post-stroke brains." (PMID 38334672, 2024). "The effects of GPR55 inactivation on BBB permeability, endothelial function, and the chemokine profile post-stroke will be explored in future studies." (PMID 38334672, 2024). "Inhibition with selective antagonist ML-193, as well as GPR55 absence (in GPR55ko), improved Bederson’s neurological scores by 60% (at day 1 after stroke, not shown) and improved survival rates post-tMCAO." (PMID 38334672, 2024).
temporal lobe epilepsy (1 paper, 2024). A localization-related (focal) form of epilepsy characterized by recurrent seizures that arise from foci within the temporal lobe, most commonly from its mesial aspect. "The current study found that GPR55 is upregulated in neurons following THC exposure, while TRPV1 is downregulated in temporal lobe epilepsy." (PMID 38404644, 2024). "To conclude, we provide here new evidence that GPR55 is upregulated in the ventral tegmental area of mice following THC exposure and that TPRV1 is downregulated in the epileptogenic focus of patients with temporal lobe epilepsy." (PMID 38404644, 2024).
tuberculosis (1 paper, 2021). A chronic, recurrent infection caused by the bacterium Mycobacterium tuberculosis. "Inconclusiveness is further perpetuated by another expression profiling study, which shows a decrease in GPR55 expression in the blood of patients with active tuberculosis." (PMID 34948125, 2021). "Furthermore, a transcriptome profiling study conducted on active tuberculosis patients T cell activation also shows downregulation of GPR55." (PMID 34948125, 2021).
ulcerative colitis (1 paper, 2021). An inflammatory bowel disease involving the mucosal surface of the large intestine and rectum. "For example, macroscopically inflamed sigmoid colon biopsies derived from patients diagnosed with ulcerative colitis were characterized by GPR55 upregulation in comparison to uninflamed hepatic flexure biopsies derived from affected patients and biopsies derived from healthy controls." (PMID 34948125, 2021).
viral hepatitis (1 paper, 2022). An acute or chronic inflammation of the liver parenchyma caused by viruses. "If the LPI-GPR55 system can be consistently linked to liver injury, it will be exciting to test whether GPR55 antagonists can provide therapeutic benefit in ALD, NAFLD, or viral hepatitis." (PMID 35636492, 2022).
cancer (77 papers, 2013 to 2026). A tumor composed of atypical neoplastic, often pleomorphic cells that invade other tissues. "This study highlights a novel role of lactate in the complex mechanisms underlying tumor progression and metastasis and identifies GPR55 as an additional lactate membrane receptor involved in cancer cell motility." (PMID 40434517, 2025). "Numerous physiological processes and diseases, such as neuropathic pain, cancer, metabolic diseases, inflammatory pain, bone growth, and neurological disorders have been linked to GPR55." (PMID 38895631, 2024). "The survival analysis revealed that GPR55 was associated with different prognostic significance for different malignant neoplasms." (PMID 37688769, 2023). "Overexpression of SPL was associated with a high dissemination rate of the cancer cells, which was, however, inhibited by additional silencing of GPR55 in this cells." (PMID 36125914, 2022). "Accordingly, the endogenous ligand for GPR55 receptors, LPI, also shows altered levels in cancers, which are a possible cause for the accumulation of GPR55." (PMID 35204820, 2022). "GPR55 signaling has previously been associated with increased proliferation and motility of cancer cells, resulting in increased aggressiveness of tumors." (PMID 34948125, 2021). "GPR55 is widely expressed in various cancers and is usually associated with the late stages and bad prognosis of the disease." (PMID 33435517, 2021). "Until now, GPR55 signaling has been implicated in cancer aggressiveness, body weight regulation, induction of liver damage, inflammation, and neural development." (PMID 34948125, 2021). "GPR55 is an orphan G-protein linked receptor that appears up-regulated in some cancer-derived cell lines and plays a pivotal role in tumor cells." (PMID 24204703, 2013). "GPR55 polymorphisms have been associated with different types of cancer." (PMID 37185752, 2023). "Moreover up-regulation of GPR55 protein was found in various types cancer and high GPR55 expression is associated with more aggressive phenotypes." (PMID 25889562, 2015). "At this dose, SR141716 can produce also modulation and internalization of GPR55, an orphan G-protein linked receptor that appears up-regulated in aggressive manner in some cancer-derived cell lines and play a pivotal role in the control of cancer cell fate." (PMID 26008966, 2015). "Interestingly, LPI and GPR55 have been associated with cancer progression." (PMID 31611800, 2019). "Functionally, GPR55 contributes to cancer progression by activating ERK signaling, which promotes proliferation, and by inducing AKT phosphorylation, a key driver of survival pathways in ovarian carcinoma (OVCAR-3) and prostate cancer cells." (PMID 40565152, 2025). "GPR-55 is overexpressed in many types of cancers and the expression correlates with cancer progression." (PMID 40109334, 2025). "GPR55 plays a crucial role in various cellular processes such as cell proliferation, migration, survival, and tumorigenesis in various cancer cell lines." (PMID 38895631, 2024). "GPR55 has been shown to promote cancer cell proliferation via the extracellular signal-regulated kinase (ERK) cascade." (PMID 38895631, 2024). "The role of GPR55 in cancer cells has been widely described, but its role in the immune TME is not well understood." (PMID 39885986, 2024). "It is interesting to note that CB2R also interacts in a heterodimeric complex with orphan GPCR, namely GPR55, and modulates cancer cell signaling as potential therapeutic interference of Δ9-THC (with appropriate dose) in cancer." (PMID 39796008, 2024). "To gain insight into the possible association between GPR55 expression in HCC and an active immune phenotype, we used a panel of genes associated with cancer immune responses to explore the immunophenotype in HCC." (PMID 37688769, 2023).